HOXA11 (homeobox A11)
Diseases named in the same sentence as HOXA11 in open-access papers (continued):
Sharing a sentence is not in itself a finding about the gene and the disease.
invasive ductal carcinomas (1 paper, 2017).
leiomyosarcoma (1 paper, 2021). An uncommon, aggressive malignant smooth muscle neoplasm, usually occurring in post-menopausal women. "Hypermethylation in the potassium voltage-gated channel, Isk-related family, member 3 (KCNE3), TSPY-like 5 (TSPYL5), Homeobox A11 (HOXA11), HOXA11 antisense RNA (HOXA11AS), HOX9, and LOC100130872, was observed in leiomyosarcoma." (PMID 35008848, 2021).
lupus (1 paper, 2022). "Further in vivo experiments showed that injection of sh-HOXA11-OS adeno-associated virus downregulated HOXA11-OS and significantly alleviated renal damage in lupus mice." (PMID 36418932, 2022). "Our experiments further verified that HOXA11-OS can positively regulate the expression of Cyr61 and autophagy by targeting miR-124-3p, thereby affecting the renal function of lupus mice." (PMID 36418932, 2022). "In the present study, HOXA11-OS was highly expressed in the kidney tissue and cells of lupus mice and in the blood of lupus patients." (PMID 36418932, 2022). "In the present study, we found that HOXA11-OS was highly expressed in kidney tissues, podocytes of lupus mice, and serum of lupus patients." (PMID 36418932, 2022). "After injection of miR-124-3p inhibition AAV, the pathological lesions in the renal tissue of mice in the Lupus + sh-HOXA11-OS + miR-124-3p inhibition group were further aggravated compared to those of mice in the Lupus + sh-HOXA11-OS group." (PMID 36418932, 2022). "Overexpression of HOXA11-OS promoted the expression of Cyr61, thus enhancing serum immunoglobulin G (IgG)-induced podocyte autophagy in lupus patients and aggravating podocyte injury." (PMID 36418932, 2022). "It was found that the expression of Cyr61 and autophagic factors was highly expressed in the kidney tissue of lupus mice and in the serum and podocytes of lupus patients, which was similar to the expression trend of HOXA11-OS but opposite to that of miR-124-3p." (PMID 36418932, 2022). "In conclusion, HOXA11-OS can mediate the expression of Cyr61 through miR-124-3p sponging, thus regulating the expression of podocyte autophagy factors and affecting the podocytes and kidney injury levels in lupus mice." (PMID 36418932, 2022). "The levels of 24 h urinary protein, BUN, Scr, as well as anti-dsDNA, ANA, and anti-Sm antibodies in the Lupus + sh-HOXA11-OS group were significantly lower than those in the Lupus group (P < 0.05), while those in the Lupus + miR-124-3p inhibition group were significantly higher (P < 0.05)." (PMID 36418932, 2022). "In addition, knockdown of HOXA11-OS in vivo obviously reduced the expression of autophagy factors in the kidney tissue of lupus mice and alleviated kidney function damage." (PMID 36418932, 2022). "The expression of HOXA11-OS, Cyr61, and the autophagy factors Beclin-1 and LC3B in the kidney tissue of lupus mice and serum of lupus patients was detected by qRT-PCR and western blotting." (PMID 36418932, 2022). "After treatment with both sh-HOXA11-OS and miR-124-3p inhibition AAV, the levels of 24 h urinary protein, BUN, Scr, as well as the levels of anti-dsDNA, ANA, and anti-Sm antibodies in mice were significantly higher than those in the Lupus + sh-HOXA11-OS group (P < 0.05)." (PMID 36418932, 2022).
lupus nephritis (1 paper, 2022). Glomerulonephritis in the context of systemic lupus erythematosus. "The present study aimed to investigate the role of HOXA11-OS in the regulation of podocyte autophagy in the development of lupus nephritis (LN) and its potential molecular mechanism." (PMID 36418932, 2022).
lymph node metastasis (1 paper, 2017). "Third, HOXA11 prefers to be hypermethylated in cases with lymph node metastasis." (PMID 28038461, 2017).
meningioma (1 paper, 2013). A generally slow growing tumor attached to the dura mater. "For the malignant meningiomas in our study, 26 genes were identified as significantly hypermethylated at promoter CpG islands, including eight genes involved in the biological pathway of neurogenesis (BARHL2, TLX3, FOXR1, HOXA11, HOXA6, HOXA9, OTX2 and PAX3)." (PMID 23349797, 2013).
metastatic tumor (1 paper, 2024). "The expression of EGR1 in the metastatic mesothelial cells was detected by multiple immunofluorescences The correlation between EGR1 and HOXA11 in the cancerous components of the metastatic tumor was analyzed (mesothelial cells were positioned by HBME1)." (PMID 38385088, 2024).
myoma (1 paper, 2013). "In agreement with this study, both HOXA10 and HOXA11 genes expression were insignificantly increased in the endometrium after removal of myoma." (PMID 24639724, 2013). "The expressions of HOXA10 and HOXA11 were significantly decreased in the presence of submucosal myoma." (PMID 24639724, 2013). "It is shown that expressions of HOXA10 and HOXA11 were decreased in the presence of myoma." (PMID 24639724, 2013).
ovarian tumor (1 paper, 2019). "Promoter methylation of HOXA10 and HOXA11, which are involved in very early ovarian tumor initiation effectively distinguished normal and malignant ovaries." (PMID 31608277, 2019).
pelvic organ prolapse (1 paper, 2015). Abnormal descent of a pelvic organ resulting in the protrusion of the organ beyond its normal anatomical confines. "Homeobox (HOX) A11 is a key transcriptional factor that controls collagen metabolism and homoeostasis in the uterosacral ligaments (USLs), and the deficient HOXA11 signalling may contribute to alterations in the biochemical strength of the USLs, leading to pelvic organ prolapse (POP)." (PMID 25630974, 2015).
renal agenesis (1 paper, 2018). Renal agenesis (RA) is a form of renal tract malformation characterized by the complete absence of development of one or both kidneys (unilateral RA or bilateral RA respectively), accompanied by absent ureter(s). "However, in mice with a single wild type copy of Hoxa11 present (Hoxa9,10−/−11+/− Hoxc9,10,11−/−), renal agenesis occurred in only 16% of mutants." (PMID 29679048, 2018).
squamous cell carcinoma (1 paper, 2013). A carcinoma arising from squamous epithelial cells. "In this study, HOXA11 hypermethylation was found at a higher prevalence in squamous cell carcinoma than adenocarcinoma and occurred at approximately 2 to 5 times higher prevalence in pT2–pT4 stage than pT1 stage." (PMID 24259349, 2013). "HOXA11 hypermethylation was found at a higher prevalence in squamous cell carcinoma than in adenocarcinoma (74% vs. 63%, respectively)." (PMID 24259349, 2013).
squamous intraepithelial lesion (1 paper, 2016). "In particular, the level of HOXA11 methylation efficaciously distinguishes high-grade squamous intraepithelial lesion cells from healthy cells; HOXA11 is also important in the embryological development of the Müllerian duct in the uterine cervix." (PMID 27792998, 2016).
sterility (1 paper, 2013). "HOXA11 is essential for implantation in the mouse as shown that disruption of this gene results in sterility." (PMID 24639724, 2013).
T-cell acute lymphoblastic leukemia (1 paper, 2024). Acute lymphoblastic leukemia of T-cell origin. "Notably, we have reaffirmed the well-established associations between transcription factors TLX1 and TLX3 with T-cell acute lymphoblastic leukemia, as well as HOXA11, PREX2, and RET with AML." (PMID 38769532, 2024).
Uterine leiomyoma (1 paper, 2013). The presence of a leiomyoma of the uterus. "Rackow and Taylor investigated the effect of uterine leiomyomas on these markers of endometrial receptivity HOXA10 and HOXA11." (PMID 24639724, 2013).
Wilms tumor (1 paper, 2022). An embryonal neoplasm characterized by the presence of epithelial, mesenchymal, and blastema components. "Expression of mENL has been found to upregulate certain Hox genes, such as HoxA11 and HoxA13, in Wilms tumor and drive oncogenesis." (PMID 35395864, 2022). "Treatment with compound 1 during the incubation significantly inhibited overexpression of HoxA11 and HoxA13, showing degradation of mENL could downregulate aberrant gene expression in Wilms tumor." (PMID 35395864, 2022).
tumor (32 papers, 2009 to 2025). "However, the underlying mechanism of HOXA11's anti-tumor activity is unclear." (PMID 28038461, 2017). "In addition, HOXA11 was associated with tumor cell migration and proliferation." (PMID 24259349, 2013). "CD44 positive GC cells and HOXA11 positive GC cells in tumor fraction were significantly increased in the mice injected with NCI-N87-HOXA11 cells and HMrSV5 cells in comparison to those of mice injected with NCI-N87-Vector cells and HMrSV5 cells (P < 0.05)." (PMID 37989866, 2024). "Low HOXA11 methylation correlates with minimal residual tumor and serves as an independent prognostic marker." (PMID 37629546, 2023). "Methylation of the HOXA11 gene promoter was significantly more frequent in GC tumor tissue (p = 0.006) than in healthy gastric mucosa." (PMID 35885590, 2022). "We observed that HOXA11 expression are significantly higher in tumor than that in normal tissues (GSE13861: P<0.0001, GSE13911: P<0.0001 and TCGA: P<0.0001)." (PMID 31695791, 2019). "The tumor burdens of HOXA11 group were obviously heavier than that of controls in the peritoneum of hosts (P<0.0001)." (PMID 31695791, 2019). "A growing body of studies observed that HOXA11 expression was downregulated in different tumor types." (PMID 29914539, 2018). "In Cox proportional hazards model, HOXA11 methylation (P<0.001), tumor size (P=0.005) and histological grade (P=0.002) were significant independent predictors of poorer clinical outcome." (PMID 28038461, 2017). "In summary, our study identifies HOXA11 as a functional tumor suppressor and an important regulator of WNT/βcatenin signaling, with frequent epigenetic inactivation in RCC tumors." (PMID 28423531, 2017). "We also found that HOXA11 functions as a tumor suppressor through antagonizing WNT/βcatenin signaling and inhibits RCC cells proliferation, migration and invasion." (PMID 28423531, 2017). "The embryonic developmentally regulated gene homeobox A11 (HOXA11) has been shown to play a direct role in platinum resistance and HOXA11 methylation correlated with suboptimal tumor debulking and OC poor prognosis." (PMID 25003579, 2014). "Moreover, if HOXA11 promoter methylation was detected in both healthy and tumor tissue, overall survival was only 28.5 months." (PMID 35885590, 2022). "Therefore, it is possible that the in vitro expression of HoxA10, HoxA11, and HoxB13 differs from that of tumor tissues in vivo." (PMID 31137902, 2019). "HOXA11 was reported to represent a potential tumor suppressor in different cancers." (PMID 29631562, 2018). "In addition, HOXA11 protein expression had an inverse relationship with the tumor clinicopathological type, with lower HOXA11 protein levels in AD tissues compared to those in AIS tissues." (PMID 28380439, 2017). "Aberrant hypermethylation and the methylation-induced down-regulation of HOXA11 may promote tumor progression." (PMID 28380439, 2017). "Therefore, to investigate the relationship between HOXA11 methylation and tumor development becomes important to further elucidate the tumorigenesis of RCC." (PMID 28423531, 2017). "Thus, our study demonstrated that HOXA11 function as a tumor suppressor in RCC, while it is frequently silenced by promoter methylation in RCC." (PMID 28423531, 2017). "The frequent down-regulation and methylation of HOXA11 in primary RCC tumors indicated that it might function as a tumor suppressor." (PMID 28423531, 2017). "Based on these observations, it is likely that HOXA11 may function as a tumor suppressor by inhibiting cell migration and cell proliferation in tumorigenesis of the lung." (PMID 24259349, 2013). "Furthermore, compared with the tumor tissues, HOXA11 expression was lower in peritumor tissues (training cohort: P<0.0001; validation cohort: P<0.0001), this tendency had also been validated by the mRNA expression level of HOXA11 in GSE13861, GSE13911 and TCGA database." (PMID 31695791, 2019). "This study supported that HOXA11 might function as a tumor suppressive gene in lung AD." (PMID 28380439, 2017).
tumor (continued). "However, the detailed mechanism of HOXA11 tumor suppressive role needs more exploration." (PMID 28423531, 2017). "Among the genes upregulated in the atypical tumor compared to the nevus were: SOX10, the receptor tyrosine kinases ROS1 and NTRK3, PLA2G2A, and HOXA11, while DUSP2, PDGFD, and ELN were downregulated." (PMID 35052351, 2021). "Downregulation of HoxA10, HoxA11, and HoxB13 in KPA cells is unexpected, because these Hox genes act as tumor-promoting genes in several types of cancers." (PMID 31137902, 2019). "Our study demonstrated the role of HOXA11 in RCC and its regulation mechanism, and strongly supports the notion that HOXA11 is a tumor suppressor for multiple carcinomas." (PMID 28423531, 2017). "Analysis of HOXA11 expression in the TCGA ACC dataset showed that it significantly correlated with Ki67 expression (P = 0.0023, r = 0.337) the proliferation gene signature (P = 0.00053, r = 0.381) and CCNE1 (P = 0.0010, r = 0.363) expression in these tumours." (PMID 33214683, 2021). "Three of them (HOXA11, MET, BRAF) are potential oncogenes currently being observed for common copy-number gains in a meta-analysis of copy number alterations across a panel of different cancer cell lines and tumor samples." (PMID 26043758, 2015).
cancer (28 papers, 2009 to 2024). A tumor composed of atypical neoplastic, often pleomorphic cells that invade other tissues. "Oncogenes ATF1 and HOXA11, and HNF4G have been implicated in multiple cancers and are involved in the positive regulation of the RNA metabolic process." (PMID 35008416, 2022). "The probability of surviving longer was observed with unmethylated HOXA11 promoter in cancer tissues (71.2 months (95% CI 57–85.3) vs. 44.3 months (95% CI 34.8–53.9) in methylated cases, log rank = 0.008)." (PMID 35885590, 2022). "The analysis showed that the HOXA11 gene promoter was significantly more frequently methylated in cancer tissue than in healthy adjacent tissue (68.7% vs. 39.4%)." (PMID 35885590, 2022). "Patients in which HOXA11 promoter in cancer tissue was methylated survived for a shorter time (44.3 months vs. 71.2 months)." (PMID 35885590, 2022). "The probability of surviving longer (71.2 months (95% CI 57–85.3) vs. 44.3 months (95% CI 34.8–53.9)) was observed with unmethylated HOXA11 promoter in cancer tissues." (PMID 35885590, 2022). "In the last few years, more and more studies show that HOXA11, through various mechanisms, is involved in the development and progression of various cancers." (PMID 35885590, 2022). "The methylation rate of HOXA11 is significant higher in cancer tissue (45.08%) than in paired normal tissue (6.82%) and matched serum specimens (16.36%)." (PMID 28038461, 2017). "The HOXA11 gene is part of the cluster named A on chromosome 7, which is a region frequently deleted in human cancers." (PMID 28380439, 2017). "First, 30 out of 264 cases have a documented family cancer history and 19 out of these 30 cases were defined as HOXA11 hypermethylated." (PMID 28038461, 2017). "This is consistent with the reports of other cancers and indicates a potential role of HOXA11 in metastasis." (PMID 28038461, 2017). "The average expression level of HOXA11 in cancer tissues was significantly lower than in normal tissues." (PMID 28038461, 2017). "The expression of HOXA11 mRNA and protein decreased in normal gastric mucosa, peri-cancer tissue and GC (P < 0.05)." (PMID 25788862, 2014). "The gene set enrichment analysis (GSEA) results indicated that HOXA1 and HOXA11 were involved in immune responses pathways and participated in the activation of a variety of classic signaling pathways related to the progression of human cancer." (PMID 34606634, 2021). "We wonder if HOXA11 might be directly involved in stemness maintenance, to investigate this possibility, we analyzed expression of critical cancer stem cell factors and pluripotency markers." (PMID 31695791, 2019). "Although HOXA11 methylation solely is under quantified as a biomarker in serum, it can be combined with other hypermethylated genes to sever as biomarkers to distinguish cancer and normal tissues in non-invasive examination." (PMID 28038461, 2017). "The hypermethylation of HOXA11 promoter region has been reported in various cancers." (PMID 28423531, 2017). "The methylation rate of HOXA11 in serum is lower than in matched cancer tissues." (PMID 28038461, 2017). "Additionally, among patients with family cancer histories, the cases with hypomethylation of HOXA11 survived longer than those with hypermethylation." (PMID 28038461, 2017). "Analysis of DEHGs in oncogenic pathways using GSCALite26 indicated that HOXD10, HOXD11, HOXD1, HOXC4, HOXC10, and HOXA11 may have a crucial role in the activation of epithelial-mesenchymal transition (EMT) in cancer, represented in the form of heatmap percentage." (PMID 35562533, 2022). "In this study, we used MethyLight assay to evaluate the methylation level of HOXA11 promoter region in paired normal and cancer tissues as well as in matched serum samples, then determined whether methylation status is associated with clinicopathological features or disease prognosis." (PMID 28038461, 2017).
cancer (continued). "The involvement of HOXD10, HOXD11, HOXD1, HOXC4, HOXC10, and HOXA11, in the cell cycle and the EMT, confirm their role in the cancer-related signaling pathways." (PMID 35562533, 2022). "In addition, HOXA11, HOXD13, and PCDHGB7 were confirmed as early methylated genes when human mammary epithelial cells (HMEC) converted into cancer cells in our previous study and in other studies." (PMID 31198475, 2019). "HOXA11, one member of HOX genes, is often deleted in human cancers." (PMID 28423531, 2017). "Moreover, prior studies revealed oncogenic function of HOXA11, HOXA13, and HOXD11 in other cancers, implicating these genes in the pathogenesis of SEPN, although further studies will be needed to elucidate their role in this setting." (PMID 29383182, 2017). "The lncRNA Homeobox A11 (HOXA11), also known as NCRNA00076, belongs to the Homeobox A (HOXA) cluster with lncRNA Homeobox A10 antisense (HOXA10AS) and HOXA Distal Transcript Antisense RNA (HOTTIP), all of which are involved in cancer proliferation, invasion, migration, and chemoresistance." (PMID 34439196, 2021). "As a biomarker combination could be more powerful than a single biomarker, we decided to evaluate, in the same EV samples, the expression of other lncRNAs whose expression in tissue impacted prognosis in other cancers studied by our group, including HOTTIP, HOTAIR, HOXA11, and HOTAIRM1." (PMID 32244977, 2020).
colorectal (2 papers, 2017). "The HOXA11 and CDKN2A genes appear to be highly promising DNA hypermethylation markers for the development of non-invasive molecular markers of lung AD." (PMID 28380439, 2017). "In summary, our results showed that the promotor regions of HOXA11, CDKN2A EX2 and EYA4 were frequently methylated in human lung AD tissues." (PMID 28380439, 2017). "HOXA11 and CDKN2A EX2 could be confirmed as DNA hypermethylation markers for lung AD." (PMID 28380439, 2017).